STAT3 (signal transducer and activator of transcription 3)
Diseases named in the same sentence as STAT3 in open-access papers (continued):
Sharing a sentence is not in itself a finding about the gene and the disease.
liver fibrosis (continued). "The activation of signal transducer and transcription factor 3 (STAT3) by IL-6 also correlates with liver fibrosis and hepatic stellate cell activation." (PMID 39968080, 2025). "Liver‐specific STAT3‐KD mice were then used to construct a CCl4‐mediated liver fibrosis model for the investigation of Ssb1 antifibrotic efficacy." (PMID 41163803, 2025). "Collectively, these results indicate that STAT3 is required for Ssb1 antifibrosis efficacy and that STAT3 is the target of Ssb1 in the treatment of liver fibrosis." (PMID 41163803, 2025). "The findings reveal that PZH ameliorates liver fibrosis by inhibiting macrophage-mediated inflammation via blockade of the EGFR/JAK1/STAT3 signaling axis, providing a mechanistic foundation for its clinical application." (PMID 41181146, 2025). "STAT3 is a key regulator of liver fibrosis; in fact, it is involved in the activation of fibroblasts and HSCs, which acquire a myofibroblast-like phenotype." (PMID 40852596, 2025). "In a CCl4-induced mouse model of liver fibrosis, IL-22 attenuated fibrosis by regulating cell polarization, inhibiting the STAT3/Erk/Akt pathway, and increasing the M2/M1-KCs ratio of KCs." (PMID 39995661, 2025). "The roles of JAK2/STAT3 and TGF-β/Smad2/3 regulatory pathways are examined specifically as it is found to be a crucial pathogenic mediator of liver fibrosis." (PMID 41293246, 2025). "In mice receiving 3‐weeks CCl4 injection, knockdown of STAT3 inhibited the expression of both fibrotic biomarkers and Gli1 compared with the un‐knockdown group, suggesting that STAT3 was important for CCl4‐induced liver fibrosis." (PMID 41163803, 2025). "Previous researchers have observed increased tyrosine 705 (Tyr 705) phosphorylation of STAT3 in liver fibrosis, which can promote HSC proliferation and activation and contribute to liver fibrogenesis." (PMID 41163803, 2025). "PZW mitigated hepatic fibrosis, with its effect associated with the inhibition of the IL-6/JAK2/STAT3 and TGF-β/Smad2/3 signaling pathways and through raising the MMP1/TIMP-1 ratio." (PMID 41293246, 2025). "Extensive experiments have shown that inhibiting STAT3 activation can effectively treat acute liver injury and liver fibrosis, making STAT3 an attractive target for therapeutic strategies." (PMID 39362602, 2024). "We showed that BDL-induced liver fibrosis leads to increased mRNA and protein expression of STAT-3 in the liver." (PMID 38549169, 2024). "Several known STAT3 inhibitors, designed to directly target hyper-phosphorylated STAT3 in cells, have been used as chemical probes to certify the role of STAT3 in CCl4-induced liver fibrosis." (PMID 38699038, 2024). "According to numerous investigations, STAT3 activity is also a survival signal that guards against lipotoxicity, whereas blocking hepatic STAT3 activation with other drugs reduces NAFLD-induced liver fibrosis." (PMID 38751599, 2024). "The top 5 most significantly activated pathways utilizing an FDR of 0.05 included pulmonary fibrosis idiopathic signaling, hepatic fibrosis signaling, osteoarthritis pathway, STAT3 pathway, and wound healing signaling." (PMID 38348743, 2024). "Consistently, we noted specific upregulation of genes enriched in ALK signaling in aged Myof (CLTC, RPS6, STAT3, etc.), which is studied extensively in liver fibrosis." (PMID 37378670, 2024). "In terms of fibrosis, inhibiting components of hepatic STAT3 activation has shown promise in attenuating hepatic fibrosis, suggesting a complex interplay in liver pathophysiology." (PMID 38633610, 2024). "Among the top 15 TFs, three TFs were closely related to the pathology of NASH and liver fibrosis, i.e., STAT3, NFκB, and PPARγ." (PMID 39338294, 2024). "The presence of exosomes containing miR-181-5p has been found to promote autophagy in liver fibrosis by inhibiting the STAT3/Bcl-2/Beclin1 pathway, resulting in reduced liver fibrosis." (PMID 39095888, 2024).
liver fibrosis (continued). "The results show that although bile duct ligation-induced liver fibrosis has led to an increase in STAT-3 expression, nicotine administration leads to an augmented increase in its expression, which is consistent with the results of mRNA expression analysis." (PMID 38549169, 2024). "Our novel observation provides new insights into the role of STAT3 ubiquitination in the progression of liver fibrosis within the context of the HIF-1 pathway, offering potential directions for targeted interventions." (PMID 39362602, 2024). "TGFRB activation leads to activation of SMAD signaling pathways, PDGFR cross-linking activates the STAT3 pathway, and both of these pathways have well-known roles in promoting hepatic fibrosis." (PMID 39656528, 2024). "TGF-β expression was increased in the liver of DDC + Veh mice but was decreased in DDC + STAT3 mice, indicating the anti-fibrotic effect of STAT3 decoy ODN on liver fibrosis." (PMID 38338338, 2024). "STX-0119, a STAT3 dimerization inhibitor, was suggested to slow the progression of liver fibrosis by preventing the activation of hepatic stellate cells." (PMID 38751599, 2024). "In our study, we observed that STAT3 played a pro-inflammatory role, which leads to the pathogenesis of liver fibrosis, and is inhibited by Tenovin-1." (PMID 38993557, 2024). "Metalloproteinase-1 levels were significantly reduced in hepatocyte-specific STAT3 knockout mice with CCl4-induced hepatic fibrosis." (PMID 36671504, 2023). "Saffron can attenuate liver fibrosis by inhibiting the JAK/STAT3 pathway and the activation of hepatic stellate cell, providing a theoretical basis for the development of new anti-fibrotic drugs." (PMID 38055395, 2023). "HSC activation-induced MMP9 production plays an important role in hepatic fibrosis through LCN2/STAT3-mediated signaling." (PMID 37960230, 2023). "JAK2/STAT3 signaling was significantly upregulated in the diethylnitrosamine-induced hepatic fibrosis of rats." (PMID 36671504, 2023). "Several studies have also found that JAK1/STAT3 interacts with the SMAD pathway to exacerbate hepatic fibrosis through TGF-β." (PMID 36671504, 2023). "To further explore the role of the JAK/STAT3 pathway in liver fibrosis, we added colivelin to the 20-μM saffron treatment group and found colivelin reversed the inhibitory effect of saffron on LX-2." (PMID 38055395, 2023). "Administration of AAV8-PGC-1α or TSA to increase PGC-1α mitigated the I/R-promoted M2-type macrophage polarization by inhibiting the IL-6/STAT3 signaling, and alleviating liver fibrosis in I/R mice." (PMID 37679346, 2023). "Previous studies have also suggested that IL6/STAT3 signaling was a promising target for treating liver fibrosis." (PMID 37860111, 2023). "More importantly, administration with AAV8-PGC-1α rescued the I/R-induced liver fibrosis by inhibiting the IL-6/JAK2/STAT3 signaling and M2-type macrophage polarization in the liver." (PMID 37679346, 2023). "JAK2/STAT3 signaling is a research hotspot in fibrotic disease, but the role of JAK2/STAT3 in the progression of hepatic fibrosis remains controversial." (PMID 38074679, 2023). "Further studies confirmed that saffron mainly reduced liver inflammation and inhibited HSCs activation by inhibiting the JAK/STAT3 pathway, thereby reducing liver fibrosis." (PMID 38055395, 2023). "In line with our finding that IF reduces hepatic LCN2, MMP9, and pSTAT3 expression in HFD-fed mice, LCN2 deletion and administration of a STAT3 phosphorylation inhibitor reduced inflammation and hepatic fibrosis." (PMID 37960230, 2023). "Many natural products that inhibit the activation of STAT3 have significant inhibitory effects on markers of liver fibrosis." (PMID 36615880, 2023).
liver fibrosis (continued). "IL-22 protects against hepatic fibrosis by activating STAT3 in hepatocytes to facilitate cell survival and proliferation, and in hepatic stellate cells to promote cell senescence." (PMID 36671504, 2023). "miR-148a released by MSC-ex regulates the function of intrahepatic macrophages and prevents liver fibrosis through the KLF6/STAT3 signaling pathway." (PMID 37328872, 2023). "The activation of STAT3 can play anti- or pro-inflammatory roles and take part in the pathogenesis of liver fibrosis in NAFLD/NASH." (PMID 36982915, 2023). "In the liver fibrosis model, MSCs-exosomes delivered miR-148a to target Kruppel-like factor 6/STAT3 pathway, leading to the differentiation of macrophages from M1 to M2 phenotype." (PMID 37670393, 2023). "Together, these data evinced that the down-regulated PGC-1α expression by I/R was associated with hepatic macrophage polarization toward M2-type and liver fibrosis in mice by enhancing the IL-6/STAT3 signaling." (PMID 37679346, 2023). "Mechanistically, MSC-derived exosomes protect liver fibrosis via delivering miR-148a to target Kruppel-like factor 6/signal transducer and activator of transcription 3 (STAT3) pathway in macrophages." (PMID 37670393, 2023). "Previous studies have reported that the activation of STAT3 plays an important role in liver fibrosis, and the upregulation of STAT3 and activation of STAT signaling pathways play a pro-inflammatory role during the pathogenesis of liver fibrosis." (PMID 38068980, 2023). "Some other inhibitor like HJC0123was proven to overcome liver fibrosis by inhibiting the phosphorylation and block the process of STAT3 activation." (PMID 37978263, 2023). "Most literature studies have reported that inhibiting JAK2/STAT3 signaling of HSC alleviates hepatic fibrosis both in vivo and in vitro." (PMID 38074679, 2023). "Research indicated that DHA can prevent fibrogenesis by inhibiting the activation of STAT3 in in vitro and in vivo models of liver fibrosis, skin fibrosis, systemic sclerosis, and pulmonary vascular remodeling, among others." (PMID 35663306, 2022). "Xiang and others reported that IL-6 can be regulated by Hepatic leukemia factor (HLF) transcription and enhance the phosphorylation of STAT3, thus activating primary hepatic stellate cells and then aggravating hepatic fibrosis." (PMID 35462928, 2022). "Meanwhile, loss of STAT5 is associated with hepatocarcinogenesis as a result of increased oncogenic STAT3 activity and induction of liver fibrosis via increased levels of TGF-β." (PMID 36374927, 2022). "Meanwhile, p-STAT3 inhibition also mitigated liver fibrosis, indicated by Masson staining and immunohistochemical staining of a-SMA." (PMID 36324154, 2022). "STAT3, a member of the same signaling pathway, has been shown to promote hepatic fibrosis, while STAT1 was found to counteract STAT3 and inhibit hepatic fibrosis." (PMID 36632136, 2022). "ERβ mediated the inhibition of major functions of LX-2 cell possibly by inhibiting the phosphorylation of STAT3, and was an important pathway through which calycosin exerted anti-liver fibrosis effect." (PMID 36207725, 2022). "It is also known that the upregulation of IL-6 and subsequent STAT3 regulatory cascades promote hepatic stellate cell (HSC) activation, causing liver fibrosis and cirrhosis." (PMID 36498787, 2022). "The p-STAT3 mediated Anxa2expression for affecting the hepatocyte pyroptosis and liver fibrosis in NASH mice." (PMID 36324154, 2022). "STAT3 is a transcription factor that activates proliferation-related cytokines involved in cell survival and growth, however, STAT3 promotes egg granulomas and liver fibrosis in Schistosoma infections." (PMID 36389166, 2022). "Recent studies have reported that STATs are associated with tissue fibrosis, including skin, lung, liver, systemic sclerosis (SSc), and STAT3 inhibitors have been shown to be effective in the Carbon tetrachloride (CCl4)-induced liver fibrosis model." (PMID 35382859, 2022).
liver fibrosis (continued). "Recent reports have indicated that STAT3 and its related cytokines have complex biological effects in liver fibrosis." (PMID 35052861, 2022). "Suppression of SOCS3 contributes to liver fibrosis by increasing fibrogenic signaling via STAT3-mediated upregulation of tissue growth factor (TGF)-β." (PMID 36303554, 2022). "In conclusion, lycorine hinders TAA-induced liver fibrosis in rats, due to—at least partly—its antioxidative and anti-inflammatory properties, along with its ability to inhibit STAT3 signaling." (PMID 35337166, 2022). "Persistent activation of STAT3 exerts a pro-inflammatory effect, which leads to various pathological manifestations in liver fibrosis." (PMID 36588728, 2022). "The analysis revealed an up-regulation of STAT3 expression in the CCl4-induced liver fibrosis tissue samples, while AHWE assisted in reducing this undesirable trend." (PMID 36588728, 2022). "The association of STAT3 and fibrosis has been reported in STZ-induced kidney fibrosis and liver fibrosis." (PMID 35585990, 2022). "This signature revealed STAT3 as a potential therapeutic target for the treatment of liver fibrosis." (PMID 35052861, 2022). "In summary, ERβ mediated the inhibition of major cellular functions of LX-2 cell possibly by inhibiting the phosphorylation of STAT3, and was an important pathway through which calycosin exert anti-liver fibrosis." (PMID 36207725, 2022). "This study provides evidence that TM4SF5-mediated STAT3 signaling promoted collagen I and laminin expression, which were involved in hepatic fibrosis/cirrhosis and eventual carcinogenesis in TM4SF5-transgenic and chemically induced mouse models." (PMID 34921636, 2021). "IL-22 signals through IL-22Rα and IL-10Rβ, triggering STAT3 signaling and has been reported to promote liver regeneration and to decrease liver fibrosis and injury." (PMID 33824326, 2021). "It has been demonstratedthat SOCS3 deletion in the liver resulted in hyperactivation of STAT3 and promotedchemical-induced liver fibrosis." (PMID 34450627, 2021). "We showed that similar to mouse models of skin, lung, and liver fibrosis, inhibition of STAT3 signaling with the small molecule TTI-101 significantly reduced T. cruzi-induced pSTAT3 levels and tissue fibrosis." (PMID 34504808, 2021). "Interleukin (IL)-17A inhibits autophagy by activating STAT3 in hepatic fibrosis; in turn, STAT3 downregulates the expression of BECN1 and VPS34, which are involved in the development of hepatic fibrosis." (PMID 33879861, 2021). "It was concluded that IL-6/STAT3 signaling prevents cholestasis and liver fibrosis and has role in regulation of hepatocyte and cholangiocyte functions in the model of sclerosing cholangitis." (PMID 33841164, 2021). "STAT3 also enhances hepatic fibrosis through the upregulation of TGF-β1 expression, which contributes to the calcification of VSMCs involving the mechanisms of TGF-β1 pathway." (PMID 34645391, 2021). "In a CCl4 model of liver fibrosis, the attenuation of fibrosis by sorafenib correlated with increased STAT3 phosphorylation in hepatocytes which was dependent on KC-derived IL-6." (PMID 34047814, 2021). "JAK2/STAT3 activation has been previously associated with the ability of TGF-β to induce pulmonary and liver fibrosis, epithelial-mesenchymal transition, and cancer cell migration/invasion." (PMID 34383713, 2021). "Based on this evidence, we evaluated the efficacy of SMSP on the STAT3 signaling pathway in DEN-induced hepatic fibrosis animal model." (PMID 32121064, 2020). "STX‐0119 is an inhibitor of STAT3 dimerization and is reported to have antifibrotic effects on a liver fibrosis model." (PMID 33112058, 2020). "Suppression of JAK2/STAT3 pathway has been showed to ameliorate liver fibrosis in rat in a recent study." (PMID 32233073, 2020).
liver fibrosis (continued). "STAT3 plays an important role in hepatic fibrosis, and STAT3 phosphorylation was observed in the liver samples of patients with liver fibrosis and cirrhosis." (PMID 33261209, 2020). "Significant immunohistochemical staining of p‐STAT3 in liver tissues was observed in hepatic fibrosis model mice, and in particular, the expression of p‐STAT3 was highlighted in the nuclei." (PMID 32233073, 2020). "Rilpivirine, a widely used anti-HIV drug, has been shown to ameliorate liver fibrosis though suppressing STAT3 and promoting STAT1-mediated HSC apoptosis." (PMID 32708044, 2020). "As s possible mechanisms, we investigated the effects of SMSP on the TGF-β and signal transducer and activator of transcription 3 (STAT3)-mediated signaling cascades, which are known to promote hepatic fibrosis." (PMID 32121064, 2020). "IL-22 can also activate signal transducer and activator of transcription 3 (STAT3) signaling in HSCs and induce their death by senescence, contributing to resolution of liver fibrosis." (PMID 32085494, 2020). "TGF‐β1/Smad2/3 and JAK2/STAT3 pathways are closely associated with the therapeutic effects of PSS, supporting its potential as an effective treatment agent for hepatic fibrosis." (PMID 32233073, 2020). "Our results are also in agreement with literature data showing a role for JAK/STAT pathway in the modulation of liver fibrosis, as in the case of STAT3 activation in hepatic stellate cells treated with IL-6 and leptin." (PMID 31861914, 2019). "Genetic disruption of Stat5 activity in a mouse model for liver fibrosis was associated with elevated TGF-β levels and enhanced growth hormone-induced Stat3 activity, ultimately contributing to the development of chronic liver disease." (PMID 31615920, 2019). "Additional evidence was provided by picrosirius red and Masson’s stainings as well as hepatic hydroxylproline quantifications, which all pointed to a significant reduction in liver fibrosis as result of STAT3 inhibition." (PMID 31776330, 2019). "Genetic deletion of MKL1 in endothelial cells or pharmaceutical inhibition of MKL1 or STAT3 or TWIST1 is sufficient to alleviate liver fibrosis in mice." (PMID 31776330, 2019). "Here we delineate a novel pathway underlying TGF-β induced EndMT and liver fibrosis in which the transcriptional modulator MKL1, in cooperation with the transcription factor STAT3 to activate TWIST1 transcription." (PMID 31776330, 2019). "The STAT3 pathway plays a critical role in hepatic fibrosis by regulating proliferation and activation of HSCs; therefore, inhibition of STAT3 has been considered as an important therapeutic target for hepatic fibrosis." (PMID 31861943, 2019). "The expressions of both interleukin (IL)-17 and its receptor IL-17RA are upregulated in hepatic fibrosis; IL-17 directly induces the production of collagen type I (Col-I) via signal transducer and activator of transcription 3 (Stat3) pathways in murine HSCs." (PMID 31623153, 2019). "Muscle-derived interleukin (IL)-6 induces transient signal transducer and activator of transcription 3 activation and a proinflammatory response that protects against liver fibrosis." (PMID 31835362, 2019). "In cell experiments, signal transducer and activator of transcription (STAT3) has been shown to be required for IL-6-mediated activation of hepatic stellate cells, eventually resulting in hepatic fibrosis." (PMID 29615085, 2018). "SMAD3 is a key of signal transduction pathways in liver fibrosis and elevated STAT3 phosphorylation in fibrosis is combined with TGFβ1 and SMAD3 activation." (PMID 30346985, 2018). "On the other hand, IL17A signaling activates STAT3 and is suggested to promote the development of liver fibrosis." (PMID 30346985, 2018). "The molecular consequences of p-SMAD3 and TGFβR2 proteins and development of liver fibrosis were demonstrated that Stat3 is essential to collaborate with SMAD3 mediating TGFβ induced fibrotic response in hepatic stellate cells." (PMID 30346985, 2018).